AP3B1 (adaptor related protein complex 3 subunit beta 1)
Description:
Subunit of non-clathrin- and clathrin-associated adaptor protein complex 3 (AP-3) that plays a role in protein sorting in the late-Golgi/trans-Golgi network (TGN) and/or endosomes. The AP complexes mediate both the recruitment of clathrin to membranes and the recognition of sorting signals within the cytosolic tails of transmembrane cargo molecules. AP-3 appears to be involved in the sorting of a subset of transmembrane proteins targeted to lysosomes and lysosome-related organelles. In concert with the BLOC-1 complex, AP-3 is required to target cargos into vesicles assembled at cell bodies for delivery into neurites and nerve terminals.
Synonyms: ADTB3A; HPS2; ADTB3; HPS; PE
Tractability: Small molecule: a structure with a bound ligand is known. Antibody: UniProt places it where antibodies can reach, with high confidence. PROTAC: ubiquitination databases record sites on it; its protein half-life has been measured.
Gene: Protein-coding gene on chromosome 5 (77,991,640 to 78,294,762, reverse strand). Ensembl gene ENSG00000132842.
Subcellular location: Cytoplasmic vesicle, clathrin-coated vesicle membrane; Golgi apparatus
Subcellular location (Human Protein Atlas): Vesicles; Cytosol; Nuclear membrane; Nucleoplasm
Pathways (Reactome):
Disease: Signaling by BRAF and RAF1 fusions
Vesicle-mediated transport: Golgi Associated Vesicle Biogenesis
Gene Ontology:
Molecular function: GTP-dependent protein binding; protein binding; protein phosphatase binding; AP-3 adaptor complex binding
Biological process: melanosome organization; anterograde axonal transport; anterograde synaptic vesicle transport; clathrin-coated vesicle cargo loading, AP-3-mediated; intracellular protein transport; melanosome assembly; platelet dense granule organization; vesicle-mediated transport; antigen processing and presentation of peptide antigen via MHC class II; gene expression; positive regulation of CD4-positive, alpha-beta T cell differentiation; protein localization to membrane; protein localization to phagocytic vesicle; protein localization to plasma membrane; response to Gram-positive bacterium; T-helper 1 cell activation; toll-like receptor 4 signaling pathway
Cellular component: lysosomal membrane; membrane; AP-3 adaptor complex; early endosome; Golgi apparatus; axon cytoplasm; clathrin adaptor complex; clathrin-coated vesicle membrane; cytoplasm; membrane coat; microvesicle
Genetic constraint (gnomAD): Loss-of-function variants: 40 observed, 88.26 expected, observed/expected ratio (o/e) 0.45, 90% interval 0.35 to 0.59. The upper end of that interval is the gene's LOEUF score, 0.59, which puts it in group 2 of 6, group 1 being the genes least tolerant of losing a copy. Missense variants: 885 observed, 1,066.9 expected, observed/expected ratio (o/e) 0.83, 90% interval 0.78 to 0.88. Synonymous variants: 329 observed, 372.59 expected, observed/expected ratio (o/e) 0.88, 90% interval 0.81 to 0.97.
Gene-disease validity (ClinGen):
ClinGen rates the evidence that AP3B1 causes each of these diseases.
Hermansky-Pudlak syndrome 2 (autosomal recessive): Definitive.
Homologues: Orthologues: chimpanzee AP3B1 (95% identical), dog AP3B1 (94% identical), macaque AP3B1 (93% identical), pig AP3B1 (92% identical), rat Ap3b1 (89% identical), mouse Ap3b1 (88% identical), rabbit AP3B1 (87% identical), guinea pig AP3B1 (86% identical), tropical clawed frog ap3b1 (73% identical), Drosophila melanogaster rb (51% identical), zebrafish ap3b1a (41% identical), Caenorhabditis elegans apb-3 (37% identical). Paralogues in human: AP3B2 (62% identical), AP1B1 (23% identical), AP2B1 (22% identical), AP4B1 (16% identical).
Diseases named in the same sentence as AP3B1 in open-access papers:
AP3B1 is named in the same sentence as 53 diseases in open-access papers, as found by Europe PMC text mining. Sharing a sentence is not in itself a finding about the gene and the disease. The quoted sentences say what the papers report.
hemophagocytic lymphohistiocytosis (7 papers, 2019 to 2024). "Another important recurrent variant identified in our cohort is AP3B1 p.T359A, which has been previously reported in a case of adult hemophagocytic lymphohistiocytosis." (PMID 30899265, 2019). "The synergistic defect of AP3B1 with UNC13D can lead to hemophagocytic lymphohistiocytosis." (PMID 38886689, 2024).
Chediak-Higashi syndrome (6 papers, 2013 to 2024). ChC)diak-Higashi syndrome (CHS) is a rare severe genetic disorder generally characterized by partial oculocutaneous albinism (OCA), severe immunodeficiency, mild bleeding, neurological dysfunction and lymphoproliferative disorder. "Defects in RAB27A, LYST, and AP3B1, leading to Griscelli syndrome type 2 (GS2), Chediak-Higashi syndrome (CHS), and Hermansky-Pudlak syndrome type 2 (HPS2), respectively, also cause defective degranulation." (PMID 31396234, 2019). "Primary HLH can be caused by mutations in a number of genes which affect cytotoxic lymphocyte granule-mediated cytotoxicity including PRF1, UNC13D, STX11, STXBP2, RAB27A (Griscelli Syndrome), AP3B1 (Hermansky-Pudlak syndrome type 2), and LYST (Chediak-Higashi Syndrome)." (PMID 31396234, 2019). "FHL with hypopigmentation includes Griscelli syndrome type 2 (GS2) (Rab27a), Chediak-Higashi syndrome (CHS) (LYST), and Hermansky-Pudlak syndrome type 2 (AP3B1)." (PMID 31244832, 2019).
Hermansky-Pudlak syndrome (6 papers, 2013 to 2024). Hermansky-Pudlak syndrome (HSP) is a multi-system disorder characterized by oculocutaneous albinism, bleeding diathesis and, in some cases, neutropenia, pulmonary fibrosis, or granulomatous colitis. "Another gene that can be mutated in Hermansky-Pudlak syndrome is AP3B1 encoding the adaptor complex three β1 subunit." (PMID 34977047, 2021). "Blood outgrowth endothelial cells from Hermansky-Pudlak syndrome patients carrying the AP3B1 mutation also lack CD63 in their WPB indicative of improper organelle maturation." (PMID 34977047, 2021). "Indeed, patients with a mutation affecting the related AP-3 complex (AP3B1 mutation, OMIM*603401), or Hermansky-Pudlak syndrome 2 (HPS2), have recently been reported to present with both recurrent bacterial infections and developmental delay, poor balance and intention tremor." (PMID 23472171, 2013).
pulmonary fibrosis (5 papers, 2021 to 2024). Chronic progressive interstitial lung disorder characterized by the replacement of the lung tissue by connective tissue, leading to progressive dyspnea, respiratory failure, or right heart failure. "AP3B1 was reported to lead to Hermansky–Pudlak syndrome type 2 both in humans and mice, associated with pulmonary fibrosis." (PMID 34573320, 2021). "Our decision to select HPS-2 mice was based on the understanding that mutations in Ap3b1 are linked to HPS pulmonary fibrosis in humans and enhance the sensitivity to bleomycin in mice." (PMID 33557836, 2021). "Apart from melanocytes, AP3B1 defects include prolonged bleeding due to the disrupted transport of the von Willebrand factor (VWF) in Weibel–Palade bodies (WPBs), immunodeficiency, and pulmonary fibrosis due to defects in lamellar body biogenesis in type II pneumocytes." (PMID 39339853, 2024).
albinism (4 papers, 2015 to 2022). A congenital disorder characterized by partial or complete absence of melanin pigment in the eyes, hair, or skin. "Pathogenic variants in both BLOC1 or AP‐3 complex (AP3B1 and AP3D1) are associated with Hermansky‐Pudlak syndrome, in which neurodevelopmental and non‐neuronal phenotypes (albinism, PID) result from lysosomal defects." (PMID 35880319, 2022). "Mutations in RAB27A, LYST, and AP3B1 give rise to FHL associated with oculocutaneous albinism, and patients with FHL are usually only screened for mutations in these genes when albinism is observed." (PMID 25312756, 2015).
Immunodeficiency (4 papers, 2013 to 2025). Failure of the immune system to protect the body adequately from infection, due to the absence or insufficiency of some component process or substance. "Hermansky Pudlak type 2 syndrome (HPS2) is a rare autosomal recessive primary immune deficiency caused by mutations on β3A gene (AP3B1 gene)." (PMID 24302998, 2013). "The importance of germline variants of AP3B1 as monogenetic causes of human inflammatory (HLH) or immunodeficiency (HPS2) syndromes suggests that the mislocalization of AP3-dependent cargo in SARS-CoV-2-infected cells could have consequences for the pathogenesis of COVID-19." (PMID 39339853, 2024).
oculocutaneous albinism (4 papers, 2015 to 2024). Oculocutaneous albinism (OCA) describes a group of inherited disorders of melanin biosynthesis characterized by a generalized reduction in pigmentation of hair, skin and eyes and variable ocular findings including nystagmus, reduced visual acuity and photophobia. "Variants in AP3B1 are a known cause of the Hermansky–Pudlak syndrome 2, a rare autosomal recessive disease characterized by platelet defects and oculocutaneous albinism (OMIM 608233)." (PMID 36231035, 2022). "In the eye, Ap3b1 was shown to regulate the ocular melanosome biogenesis, including that in the RPE, with genetic Ap3b1 abrogation leading to oculocutaneous albinism." (PMID 38253888, 2024).
breast carcinoma (2 papers, 2015 to 2023). "AP-3 complex subunit beta-1 (AP3B1) is upregulated in hepatocellular carcinoma and is a proven target for miR-9 in breast cancer cells." (PMID 36979661, 2023). "Among these genes, AP3B1, ONECUT2 and IL-6 were already confirmed to be direct targets of miR-9 in breast cancer, insulin-producing cells, and cervical adenocarcinoma, respectively, which demonstrated the reliability of our screening strategy." (PMID 26547929, 2015).
COVID-19 (2 papers, 2021 to 2024). A disease caused by infection with severe acute respiratory syndrome coronavirus 2. "The total percentage of COVID-19 patients with variants in UNC13D or AP3B1, two typical HLH genes, was dramatically higher in high-level cytokine group than in low-level group (33.3 vs. 5.7%, P < 0.001)." (PMID 33867526, 2021). "Germline variants in UNC13D and AP3B1 were associated with the development of severe cytokine storms, fatal outcomes in COVID-19." (PMID 33867526, 2021). "Importantly, germline variants in AP3B1 have been associated with the development of severe cytokine profiles and fatal outcomes in COVID-19, suggesting that AP-3 and LRO trafficking in the context of infection warrants further investigation." (PMID 39339853, 2024). "We conducted whole-exome sequencing in 233 hospitalized COVID-19 patients and identified four PID gene (UNC13D, AP3B1, RNF168, DHX58) variants were significantly enriched in COVID-19 patients experiencing severe cytokine storms." (PMID 33867526, 2021).
diabetes (2 papers, 2021). "AP3B1 expression was low in females, COPD and diabetes but high in smoking, hypertension and aged individuals." (PMID 33684134, 2021). "AP3B1 is known to have variants associated with fasting insulin and HOMA-IR in African Americans without diabetes." (PMID 34863089, 2021).
Familial hemophagocytic lymphohistiocytosis (2 papers, 2013 to 2023). Familial Hemophagocytic lymphohistiocytosis (FHL) is a rare primary immunodeficiency characterized by a macrophage activation syndrome (see this term) with an onset usually occurring within a few months or less common several years after birth. "Additionally, and in agreement with a previous report, we also detected rare heterozygous mutations in some genes, including AP3B1, PRF1, LYST and DOCK8, that are associated with familial hemophagocytic lymphohistiocytosis in patients with MIS-C." (PMID 36282598, 2023).
hepatocellular carcinoma (2 papers, 2020 to 2023). A malignant tumor that arises from hepatocytes. "miR-9 is frequently down-regulated in primary hepatocellular carcinoma and its restoration retards cell proliferation and migration by targeting IL-6, AP3B1, TC10, OC2, IGF2BP1, MYO1D, and ANXA241." (PMID 32393810, 2020).
Intellectual disability (2 papers, 2023 to 2025). "RNS neurophenotypes share some features with AP3B1 and AP3M1 LoF, including development delay/intellectual disability, seizures, and hypotonia." (PMID 37240249, 2023).
neutropenia (2 papers, 2022 to 2024). A decrease in the number of neutrophils found in the blood. "Mutations in AP3B1 lead to incomplete formation of the AP-3 complex, resulting in lysosomal-related cell dysfunctions, including neutropenia, impaired platelet function, and impaired NK cell function." (PMID 35928686, 2022). "The relationship and internal mechanism between periodontitis and neutropenia caused by AP3B1 mutation need to be further explored, which may shed light on the function and underlying mechanism of neutrophils in periodontitis." (PMID 35928686, 2022). "Neutropenia is one of the major distinguishing features of HPS2, as it confers from mutations in the AP3B1 gene (autosomal recessive inheritance)." (PMID 39171069, 2024). "The diagnosis of HPS-2 is confirmed by pathogenic variants in AP3B1, absence of platelet dense granules, and clinical symptoms, including OCA and neutropenia." (PMID 35928686, 2022).
Primary hemophagocytic lymphohistiocytosis (2 papers, 2022 to 2024). "Rare heterozygous missense variants in genes responsible for primary hemophagocytic lymphohistiocytosis (LYST, STXBP2, PRF1, UNC13D, AP3B1, and DOCK8) were found in patients with MIS-C." (PMID 38397896, 2024). "Thirty-nine children were diagnosed with MIS-C, and 25.4% of the 39 MIS-C patients harbored rare heterozygous missense mutations either in primary hemophagocytic lymphohistiocytosis (pHLH) genes (LYST, STXBP2, PRF1, UNC13D, AP3B1) or the HLH-associated gene DOCK8 (four variants)." (PMID 35336791, 2022).
viral infection (2 papers, 2024 to 2025). "The regulation of MHC antigen processing and presentation during viral infection involves four genes: AP3B1, B2M, CD1A, and CD1D." (PMID 41155393, 2025).
AIDS (1 paper, 2024). A syndrome resulting from the acquired deficiency of cellular immunity caused by the human immunodeficiency virus (HIV). "Interestingly, in a genome-wide association study, AP3B1 single nucleotide polymorphisms were found to have significant association with HIV-1 subtype C acquisition in populations in Botswana or were highly associated with AIDS progression in a United States–European American cohort." (PMID 39339853, 2024).
coagulopathies (1 paper, 2021). "Overall, diseases associated with a putative loss-of-function of NETs suggest mechanistic roles for AP3B1, coronin-1 and integrin β2 in regulating NET-mediated coagulopathies in the lung alveolar and peri-alveolar areas." (PMID 33684134, 2021).
colon cancer (1 paper, 2017). "To assess their implication we performed small hairpin RNA (shRNA) knockdown of the putative rate-limiting proteins, AP3B1 and GTF2E2, in shRNA transfected HCT116 human colon cancer cell lines followed by western blot." (PMID 29032074, 2017).
influenza (1 paper, 2023). An acute viral infection of the respiratory tract, occurring in isolated cases, in epidemics, or in pandemics; it is caused by serologically different strains of viruses (influenzaviruses) designated A, B, and C, has a 3-day incubation period, and usually lasts for 3 to 10 days. "COVID‐19 together with non‐COVID‐19 DAD and OFP differed from influenza and UIP by profound collagenous fibrosis and germline variance observed for severe disease progression, such as for AP3B1." (PMID 37519267, 2023).
Interstitial pneumonitis (1 paper, 2019). "The HPS2 patient donor had compound heterozygous nonsense mutations in exon 15 and 18 of the AP3B1 gene and he was histologically diagnosed with nonspecific interstitial pneumonitis at 20 months of age." (PMID 30773483, 2019).
liver cancer (1 paper, 2023). An epithelial or non-epithelial malignant neoplasm that arises from the liver. "At present, there is no research on AP3B1 and RNP1 in liver cancer, which is worth exploring." (PMID 38086834, 2023).
lung carcinoma (1 paper, 2021). "RAB27A expression was found altered in all studied conditions, while AP3B1 expression was also found altered in all conditions except one, lung cancer." (PMID 33684134, 2021).
male infertility (1 paper, 2024). The inability of the male to effect fertilization of an ovum after a specified period of unprotected intercourse. "Three additional genes (PCSK4, AP3B1, and DLK1) were identified as novel relevant players in human male infertility using the gene-wise burden test approach (P < 5.56E−04)." (PMID 39678461, 2024).
neuroblastoma (1 paper, 2016). Neuroblastoma (NB) is the most common solid, extracranial childhood tumor. "Mouse neuroblastoma N2a cells pretreated with LRRK2, AP3B1, or non-targeting siRNA were surface-labeled with an Alexa488-conjugated antibody to the extracellular domain of LAMP1 for 30 min at 4 °C." (PMID 27424887, 2016).
infection (4 papers, 2016 to 2024). The state of being infected such as from the introduction of a foreign agent such as serum, vaccine, antigenic substance or organism. "Given the consequential roles of AP-3 in the replication of diverse pathogens, we focused on validating the interaction between SARS-CoV-2 E protein and AP3B1 and aimed to understand the role of AP3B1 during the infection cycle of SARS-CoV-2." (PMID 39339853, 2024). "To test whether AP3B1 supports or inhibits viral replication, we ectopically expressed the HA-tagged full-length (FL) AP3B1 in ACE2-expressing A549 cells followed by infection with SARS-CoV-2." (PMID 39339853, 2024). "Six of these genes were predicted to be involved in host immune response to infection: PTN on BTA4, AP3B1 on BTA10, HSF1on BTA14, SHARPIN on BTA14, TRAF4 on BTA20 and FKBP5 on BTA23." (PMID 26960806, 2016). "Thus, interactions between AP3B1 and SARS-CoV-2 might influence the clinical outcomes of infection." (PMID 39339853, 2024).
tumor (3 papers, 2016 to 2024). "AP3B1 expression is controlled by the anti-tumor microRNA-9 in breast cancer and its copy number increases in patients with neurofibromatis type I, an autosomal dominant disorder causing tumor development." (PMID 34565296, 2021). "Additionally, considering that loss of chromosome frequently occurred in many cancers can result in genomic chromosomal instability, it implies that the loss of the reference gene loci in the tumor may cause a false-positive elevated ratio of MET:AP3B1 in ddPCR, rather than high MET copy number." (PMID 26765781, 2016).
neurological disorders (1 paper, 2025). "However, no human neurological disorders have yet been associated with combined variants in AP3B1 and TRAPPC9." (PMID 41300827, 2025).
AP3B1 also shares sentences with these, for which no sentence is quoted: Griscelli syndrome type 2 (3 papers); AMeD syndrome (1); amyotrophic lateral sclerosis (1); Autoimmunity (1); bacterial infections (1); bone marrow failure (1); cancer (1); cervical adenocarcinoma (1); depression (1); developmental delay (1); dwarfism (1); Griscelli syndrome (1); Headache (1); Hermansky-Pudlak syndrome 2 (1); Hypertension (1); LIG4 syndrome (1); Menkes syndrome (1); Myelodysplasia (1); neurodegenerative disease (1); oculocutaneous albinism type 1 (1); Pancytopenia (1); periodontitis (1); Rothmund-Thomson syndrome (1); Thrombocytopenia (1); X-linked lymphoproliferative syndrome (1).